CCR7 (C-C motif chemokine receptor 7)
Diseases named in the same sentence as CCR7 in open-access papers (continued):
Sharing a sentence is not in itself a finding about the gene and the disease.
bladder cancer (14 papers, 2015 to 2026). "Univariate regression analysis suggested that the TNM stage, CCR7 expression in the cell membrane and lymph node positivity were strongly associated with bladder cancer." (PMID 38762550, 2024). "Our results demonstrated that the CXCL14/CCR7/STAT3 axis significantly promotes the glycolytic shift in bladder cancer cells by upregulating the expression of HK2 and LDHA, two key glycolytic enzymes." (PMID 40898244, 2025). "Mechanistically, CAF-secreted CXCL14 engaged CCR7 on bladder cancer cells, triggering STAT3 phosphorylation and consequently upregulating the DNA repair gene ERCC4 to promote cisplatin resistance." (PMID 40898244, 2025). "The CXCL14/CCR7/STAT3 axis critically mediates cisplatin resistance in bladder cancer through dual modulation of DNA repair and glycolytic metabolism." (PMID 40898244, 2025). "Collectively, our results suggest that CAF-derived CXCL14 targets CCR7 in bladder cancer cells, enhancing ERCC4 transcription through JAK2/STAT3 activation and subsequently binding to the ERCC4 promoter region." (PMID 40898244, 2025). "Through mRNA and protein expression analysis, we observed that bladder cancer tissues had a significantly higher CCR7 expression level than adjacent tissues." (PMID 38762550, 2024). "Subsequently, multivariate Cox regression analyses showed that CCR7 expression in the cell membrane and lymph node positivity were key influences on bladder cancer prognosis." (PMID 38762550, 2024). "In vitro experiments determined that CCL21/CCR7 activation enhanced urinary bladder cancer cell migration/invasion; however, this behavior was reversible upon CCR7 inhibition." (PMID 35203305, 2022). "Using immunohistochemical staining, CCR7 was found to be elevated in urinary bladder cancers, which significantly correlated with positive lymph node status, tumor grade and lower overall survival." (PMID 35203305, 2022). "In a follow-up study using clinical samples and T-24 bladder cancer cell lines, the same group reported that the microRNA, miR-199a-5p, which targets CCR7 mRNA for deactivation, was downregulated in bladder cancers." (PMID 35203305, 2022). "CCL21/CCR7 enhanced bladder cancer cell proliferation and facilitated migration and invasion by increasing levels of MMP-2 and MMP-9." (PMID 33146700, 2020). "Clinicopathological data also show that chemokines and their receptors are involved in tumor lymphatic metastasis; for example, CCL21/CCR7 expression is related to poor outcomes in urinary bladder cancer." (PMID 29599774, 2018). "This study was aimed to further investigate the effects of miR-199a-5p on the cell metastasis mediated by CCR7 in bladder cancer." (PMID 27814720, 2016). "miR-199a-5p downregulation and CCR7 upregulation were firstly observed in bladder cancer samples and cell lines." (PMID 27814720, 2016). "Quantitative Real Time PCR (qRT-PCR) was firstly performed to identified the expression of miR-199a-5p and CCR7 in human bladder cancer samples and cell lines." (PMID 27814720, 2016). "Although miR-199a-5p in this study showed a good control to cell metastasis by targeting CCR7 in human bladder cancer, it should be noted that this study only revealed the effect of miR-199a-5p on cell metastasis." (PMID 27814720, 2016). "Taken together, our findings elucidate a novel role of miR-199a-5p in the suppression of cell metastasis through regulation MMP-9 and EMT-related genes by targeting CCR7 in bladder cancer." (PMID 27814720, 2016). "Contrary to miR-199a-5p, the expression of CCR7 was 6.60-fold and 10.53-fold higher in tumour tissues and bladder cancer cells compared with that in paired adjacent normal tissue or normal epithelial cell line SV-HUC-1, respectively." (PMID 27814720, 2016). "Our findings added newer insights into the multifaceted role played by miR-199a-5p/CCR7 in bladder cancer, prompting for the first time this miRNA/chemokine axis that regulates cell metastasis." (PMID 27814720, 2016).
bladder cancer (continued). "Collectively, these results add newer insights into the multifaceted role played by miR-199a-5p/CCR7 in bladder cancer, prompting for the first time this miRNA/chemokine axis that regulates cell metastasis." (PMID 27814720, 2016). "We also found that CCR7 was involved in the development and progression of bladder cancer (unpublished data)." (PMID 25798926, 2015). "To further confirm whether CAFs regulate bladder cancer cell chemoresistance through CCR7 induced STAT3 activation, we employed CAFs infected with shNC or shCXCL14." (PMID 40898244, 2025). "Additionally, the interaction between CXCL14 and CCR7 in bladder cancer cells was further validated by fluorescence confocal microscopy." (PMID 40898244, 2025). "Similarly, another microRNA, miR-1275, also elevated CCR7, leading to a more aggressive cancer cell phenotype; and, in bladder cancer, decreased miR-199a-5p led to increased CCR7 and increased MMP-9 and elevated cell migration." (PMID 35203305, 2022). "High expression of RRBP1 reduced the overall survival of patients with bladder cancer, which might, at least in part, be due to its effects on CCR7." (PMID 35203305, 2022). "In bladder cancer, CCR7 enhanced pro-survival Bcl-2, while decreasing pro-apoptotic Bax proteins." (PMID 35203305, 2022). "While not well defined, RRBP1 knockdown led to an elevation in CCR7 mRNA as well; however, the levels of CCR7 protein decreased presumably due to reduced CCR7 mRNA translation in the low RRBP1 environment with the consequence of attenuated bladder cancer cell migration and invasion." (PMID 35203305, 2022). "For instance, miR-199a-5p is known to inhibits VEGF-induced tumorigenesis and suppresses human bladder cancer cell metastasis by targeting C-C chemokine receptor type 7 (CCR7); this miRNA is also documented to target ETS-1 and suppresses HMEC angiogenesis by inhibiting VEGF and HGF signaling." (PMID 31188886, 2019). "In addition, both miR-199a-5p downregulation and CCR7 upregulation were significantly involved in bladder cancer clinicopathological features." (PMID 27814720, 2016). "In addition, both CCR7 upregulation and miR-199a-5p downregulation were significantly involved in bladder cancer clinicopathological features." (PMID 27814720, 2016). "To test whether miR-199a-5p could directly interact with CCR7 in bladder cancer cells, we found that the 3′UTR of CCR7 contained a potential miR-199a-5p binding site through bioinformatics software (microRNA.org)." (PMID 27814720, 2016). "Next, we detected CCR7 expression in human bladder cancer tissue samples and cell lines." (PMID 27814720, 2016). "Additionally, the combination of cisplatin-based chemotherapy with CCR7 or STAT3-targeted therapies may offer a more effective treatment strategy for patients with bladder cancer." (PMID 40898244, 2025). "CCL21/CCR7 may promote bladder cancer development and metastasis." (PMID 25798926, 2015). "Our results indicate that CCL21/CCR7 may promote bladder cancer development and metastasis." (PMID 25798926, 2015). "However, the possible role of CCL21/CCR7 in bladder cancer development and progression remains unclear." (PMID 25798926, 2015). "Through bioinformatics predictions combined with experimental validation, we identified a novel CXCL14 receptor, a G protein-coupled receptor named CCR7, which appears to be a critical mediator of CAF-driven chemoresistance in bladder cancer cells." (PMID 40898244, 2025). "Specifically, CXCL14 activates the CCR7/JAK2/STAT3 axis, leading to the upregulation of ERCC4 transcription, which promotes DNA damage repair in bladder cancer cells, thereby facilitating the development of chemoresistance." (PMID 40898244, 2025). "Taken together, our results suggest that disrupting the CXCL14/CCR7/STAT3 signaling axis, both in vitro and in vivo, enhances DNA damage and increases cisplatin sensitivity in bladder cancer." (PMID 40898244, 2025).
bladder cancer (continued). "Like its reported role in bladder cancer, a study found that MMP-9 is upregulated by CCR7 in the PCI-37B head and neck squamous carcinoma cell line." (PMID 35203305, 2022). "In T24 human bladder carcinoma cells, CCL21 activation of CCR7 promoted cell proliferation and migration mediated by increased levels of matrix metalloproteinases 2 and 9 (MMP-2 and MMP-9)." (PMID 35203305, 2022). "In this study, we provided evidence that miR-199a-5p/CCR7 plays an essential role in both the suppression of the EMT process and the metastatic ability of bladder cancer cells." (PMID 27814720, 2016). "C-C chemokine receptor type 7 (CCR7) overexpression correlated with lymphatic metastasis and poor prognosis is a major obstacle to bladder cancer treatment." (PMID 27814720, 2016). "Unfortunately, an experiment to add back RRBP1 was not conducted to validate the role of CCR7 in bladder cancer migration/invasion." (PMID 35203305, 2022). "On the other hand, we also observed that miR-199a-5p could directly target the 3′UTR of CCR7 and regulate the expression of MMP-9 and EMT-related proteins like vimentin and E-cadherin, eventually suppress the progression of bladder cancer." (PMID 27814720, 2016). "However, to the best of our knowledge, the relationship between miR-199a-5p and CCR7 in bladder cancer has not been reported to date." (PMID 27814720, 2016).
head and neck squamous cell carcinoma (14 papers, 2012 to 2026). A squamous cell carcinoma that arises from any of the following anatomic sites: lip and oral cavity, nasal cavity, paranasal sinuses, pharynx, larynx, and salivary glands. "Another study revealed that hsa‐let‐7e‐5p inhibited the progression of head and neck squamous cell carcinoma by targeting CCR7 expression." (PMID 41551936, 2026). "The expression level of CCR7 in head and neck squamous cell carcinoma (HNSCC) was higher than that in normal tissue but differed between individual cancer stages according to the TCGA database." (PMID 38539232, 2024). "The hsa-let-7e-5p was found to be a tumor suppressor to inhibit the progression of head and neck squamous cell carcinoma by targeting CCR7 expression and a potential prognosis marker for rectal carcinoma with liver metastases." (PMID 35601497, 2022). "hsa‐let‐7e‐5p was found to inhibit the progression of head and neck squamous cell carcinoma by significantly decreasing CCR7 protein expression." (PMID 33630421, 2021). "For example, increased expression of CCL19 and CCL21 by lymphatic endothelium in squamous cell carcinoma of the head and neck (SCCHN) promoted dissemination of CCR7+ tumor cells to secondary lymphoid tissues." (PMID 34503058, 2021). "Another study found that hsa-let-7e-5p as a tumor suppressor could inhibit the progression of head and neck squamous cell carcinoma by targeting CCR7 expression." (PMID 36570001, 2022). "TWIST seems to be a pivotal transcription factor that may positively regulate the expression of CXCR4 and CCR7 genes during lymph node metastasis, and its expression is significantly correlated with the clinical stage of head and neck squamous cell carcinoma." (PMID 21743395, 2012). "In head and neck squamous cell carcinoma (HNSCC), miR-20a-5p functioned as an oncogene by downregulating TNFRSF21 and upregulating CCR7 expression." (PMID 37829050, 2023). "Notably, in head and neck squamous cell carcinoma (HNSCC), the CCR7/DUSP1 signaling axis regulates iCAFs activity, enhancing tumor cell growth potential." (PMID 40755775, 2025). "In squamous cell carcinoma of the head and neck (SCCHN), E‐cadherin and vimentin are proved to be downstream target molecules of chemokine receptor 7 (CCR7)‐Pyk2, which may participate in the modulation of EMT, migration, and invasion of cancer cells." (PMID 31368612, 2019).
non-small cell lung carcinoma (14 papers, 2010 to 2024). A group of at least three distinct histological types of lung cancer, including non-small cell squamous cell carcinoma, adenocarcinoma, and large cell carcinoma. "Extracellular signal-regulated protein kinase (ERK) and AKT are major downstream signaling molecules activated by CCR7 in different cell types and are important for CCR7-induced prevention of apoptosis of human non-small cell lung cancer cells." (PMID 24915301, 2014). "Our previous study demonstrates that CCR7 is highly expressed in human non-small cell lung cancer (NSCLC) cells, and that CCL21/CCR7 promotes proliferation of A549 and H460 cells of NSCLC via extracellular signal-regulated kinase (ERK) pathway." (PMID 22438908, 2012). "C-C chemokine receptor 7 (CCR7) contributes to the survival of certain cancer cell lines, but its role in the proliferation of human non-small cell lung cancer (NSCLC) cells remains vague." (PMID 21698152, 2011). "Furthermore, extracellular signal-regulated kinase (ERK1/2) pathway is involved in cell cycle progression and survival of non-small cell lung carcinoma cells resulting from CCR7 activation." (PMID 25744065, 2015). "As cancer cells can utilize CCR7 to metastasize in lymph nodes, we used the human non-small cell lung carcinoma cell line H1299 expressing CCR7-eGFP or not as model to study cancer cell migration." (PMID 30518137, 2018). "Previously, we confirmed that C-C chemokine receptor 7 (CCR7) promotes cell proliferation via the extracellular signal-regulated kinase (ERK) pathway, but its role in apoptosis of non-small cell lung cancer (NSCLC) cell lines remains unknown." (PMID 22438908, 2012). "It has been proven that CC chemokine receptor 7 (CCR7) is closely related with the lymph node metastasis of non-small cell lung cancer (NSCLC), but the mechanism of NSCLC metastasis is not very clear." (PMID 21081040, 2010).
squamous cell carcinoma (13 papers, 2007 to 2025). A carcinoma arising from squamous epithelial cells. "It has been reported that lymphocyte activation is associated with CCR7 down-regulation in squamous cell carcinoma of the head and neck, causing the functional cells to reside in tumour sites and exert immune functions." (PMID 26673957, 2015). "It has been shown that AP1 complex plays a role in the regulation of CCR7 expression in metastatic squamous cell carcinoma cells and gallbladder cancer cells." (PMID 30781353, 2019). "The aim of this study was to evaluate the expression of CC chemokine receptor 7 (CCR7) in squamous cell cancer of the tonsil with respect to patterns of spread, relapse-free, overall and disease-specific survival." (PMID 17687340, 2007). "Besides, in the Hp-GC-related network, hsa-miR-125a-5p was described to upregulate CCR7 and promote the development of squamous carcinoma in the head or neck." (PMID 33282942, 2020). "Similarly, PTK2B has been reported to be involved in the CCR7‐mediated regulation of metastasis in squamous cell carcinoma and was found to be downregulated in our study." (PMID 29193607, 2018). "Therefore, in this study we have evaluated the expression of CCR7 in squamous cell cancer of the tonsil with particular reference to the development of synchronous and/or metachronous cervical nodal metastases and systemic relapse." (PMID 17687340, 2007). "Tongue squamous cell carcinoma tissues and different cell lines detected the expression of CCR7 when compared to normal oral mucosa with no CCR7 expression." (PMID 30417146, 2018).
cervical cancer (12 papers, 2016 to 2024). A primary or metastatic malignant neoplasm involving the cervix. "In contrast, CCR7 expression in cervical cancers could be linked to improved or reduced overall survival, dependent upon the study." (PMID 35203305, 2022). "For instance, the expression of CCR7 in cervical cancer tumor cells can direct them toward lymph nodes that express CCL21, one of its chemokine ligands." (PMID 39200672, 2024). "Among the mechanisms involved, there was evidence that E6 and E7 proteins from HPV downregulates CCR7 by upregulating IL-6 in cervical cancer cell lines." (PMID 36831674, 2023). "In the cervical cancer relevant immune microenvironment analysis, both CCR7 and CD79A were selected as representative genes concerning survival outcomes." (PMID 37988195, 2023). "Our results demonstrated that radiotherapy of cervical cancer induced an increase in the number of TAMs and a change in their subtype from the M2-like to the M1-like phenotype (increased expression of CCR7 and decreased expression of CD163)." (PMID 35062905, 2022). "In contrast to earlier studies, analysis of differential gene expression suggested an important role of CCR7 in protection from cervical cancer." (PMID 35203305, 2022). "Our experiments demonstrate that EVs from cervical cancer patients after radiotherapy contributed to the M2-like to M1-like phenotype transition (increased expression of CCR7, TNFα and iNOS, and decreased expression of CD163 and IL-10)." (PMID 35062905, 2022). "We identified 79 prognostic TIME-related genes in cervical cancer and validated 4 genes (CCR7, CD28, PD-1, and ZAP70)." (PMID 32733542, 2020). "In a screen of 1367 differentially expressed genes in cervical cancer in The Cancer Genome Atlas (TCGA) database, 79 prognostic differentially expressed genes were found, and four of these genes, including CCR7, were further validated in the Gene Expression Omnibus database." (PMID 35203305, 2022). "Thus, cervical cancer-derived IL-6 immobilizes dendritic cells in the tumor stroma via CCR7 suppression facilitating local MMP-9 production." (PMID 28895886, 2017). "CCL19 has also been shown to be overexpressed in cervical cancer tissue and cell lines with siRNA-induced a reduction in CCL19 inhibiting cervical cancer cell proliferation and increased levels of apoptosis, suggesting that CCL19 via CCR7 activation is a driving force of cervical cancer progression." (PMID 35203305, 2022). "Though there lacked reports on CCR7 levels of LCs after HPV infections, cervical cancer cells suppressed the induction of CCR7 in phenotypically mature dendritic cells (DCs), while specific co-stimulatory molecules upregulated CCR7 expression on LCs surface." (PMID 36311788, 2022). "Notably, both CCR7 and MMP-9 up-regulation are mediated by IL-6 from the cervical cancer cells." (PMID 28895886, 2017). "However, we did not observe increased CCR7 expression in cervical cancer cells by immunoflurosence staining (data not shown)." (PMID 27713149, 2016).
Insulin resistance (12 papers, 2016 to 2024). Increased resistance towards insulin, that is, diminished effectiveness of insulin in reducing blood glucose levels. "It was shown that ccr7−/− mice in an obese mouse model were able to counteract high-fat diet-induced weight gain and insulin resistance by increasing calorie consumption and decreasing inflammatory activity." (PMID 39334887, 2024). "Previous studies have shown that CCR7-positive immune cell accumulation promotes a local inflammatory response in the pancreas, thereby leading to insulin resistance." (PMID 38762550, 2024). "Through the use of animal models, it was possible to demonstrate the involvement of CCR7 in the process of chronic inflammation and insulin resistance." (PMID 35069589, 2021). "Indeed, obese Flt3l–/– mice lacking DCs and Ccr7–/– mice with impaired DC migration displayed reduced metabolic inflammation and insulin resistance, suggesting they have a central role in the development of metabolic dysfunctions." (PMID 37140993, 2023).